EXOC3L2 (exocyst complex component 3 like 2)
Synonyms: XTP7; FLJ36147; BMRS
Tractability: No criterion of Open Targets' tractability assessment is met for any kind of drug.
Gene: Protein-coding gene on chromosome 19 (45,212,370 to 45,245,407, reverse strand). Ensembl gene ENSG00000283632.
Subcellular location (Human Protein Atlas): Golgi apparatus; Vesicles; Mid piece; Nucleoli; Nucleoplasm
Gene Ontology:
Molecular function: protein binding
Biological process: exocytosis
Cellular component: exocyst
Genetic constraint (gnomAD): Loss-of-function variants: 17 observed, 37.09 expected, observed/expected ratio (o/e) 0.46, 90% interval 0.31 to 0.69. The upper end of that interval is the gene's LOEUF score, 0.69, which puts it in group 2 of 6, group 1 being the genes least tolerant of losing a copy. Missense variants: 534 observed, 537.91 expected, observed/expected ratio (o/e) 0.99, 90% interval 0.92 to 1.07. Synonymous variants: 253 observed, 228.63 expected, observed/expected ratio (o/e) 1.11, 90% interval 1 to 1.23.
Homologues: Orthologues: chimpanzee EXOC3L2 (99% identical), dog EXOC3L2 (92% identical), pig EXOC3L2 (91% identical), rat Exoc3l2 (87% identical), mouse Exoc3l2 (86% identical), guinea pig EXOC3L2 (79% identical), macaque EXOC3L2 (50% identical), zebrafish exoc3l2b (39% identical), tropical clawed frog exoc3l2 (35% identical), zebrafish exoc3l2a (18% identical). Paralogues in human: EXOC3L4 (23% identical), EXOC3L1 (21% identical), TNFAIP2 (19% identical), EXOC3 (18% identical).
Diseases named in the same sentence as EXOC3L2 in open-access papers:
EXOC3L2 is named in the same sentence as 22 diseases in open-access papers, as found by Europe PMC text mining. Sharing a sentence is not in itself a finding about the gene and the disease. The quoted sentences say what the papers report.
Alzheimer disease (8 papers, 2015 to 2025). A progressive, neurodegenerative disease characterized by loss of function and death of nerve cells in several areas of the brain leading to loss of cognitive function such as memory and language. "Recent genome-wide association studies revealed an association between the EXOC3L2 rs597668 variant and Alzheimer’s disease in European and Asian populations." (PMID 36362885, 2022). "Recent genome-wide association studies have established the association between EXOC3L2 rs597668 variant and Alzheimer's disease (AD) in European population." (PMID 28423615, 2017). "EXOC3L2 was previously considered one of the susceptibility genes for Alzheimer’s disease, and its study of cancer may become a new direction for future research." (PMID 40426913, 2025). "The gene EXOC3L2 has been associated with late onset Alzheimer disease (LOAD) in GWAS." (PMID 25765079, 2015). "Since Exoc3l2 was shown to contribute to brain development by our study, it will be interesting to examine whether Exoc3l2 also plays a role in human brain disorders, such Alzheimer’s disease." (PMID 36362885, 2022). "EXOC3L2 has not been previously reported to modulate dyslipidemia but EXOC3L2, APOE, TOMM40, and PVRL2 are reported to be Alzheimer’s disease-susceptibility genes." (PMID 32727492, 2020). "A polymorphism (rs597668) near the EXOC3L2 gene locus has been associated with Alzheimer’s disease (AD), and while no role for EXOC3L2 in AD has yet been proposed it may prove relevant to consider the expression and functionality of alternatively spliced EXOC3L2 isoforms in the context of AD." (PMID 30086153, 2018).
ciliopathy (3 papers, 2016 to 2023). A genetic disorder of the cellular cilia or the cilia anchoring structures, the basal bodies, or of ciliary function. "Analysis of a large cohort of patients with ciliopathy spectrum revealed novel candidate genes for ciliopathies, including EXOC3L2." (PMID 37085629, 2023). "EXOC3L2, however, has been proposed as a novel candidate gene for a lethal ciliopathy phenotype that resembles Meckel-Gruber syndrome." (PMID 34974531, 2022). "Of the remaining 40 families, nine (22.5%) had variants in eight novel candidate ciliopathy genes (TXNDC15, TRAPPC3, EXOC3L2, FAM98C, C17orf61, LRRCC1, NEK4, and CELSR2)." (PMID 27894351, 2016). "In another study, novel mutations of EXOC3L2 were found in two families with Dandy–Walker malformation (DWM), which primarily affects cerebellar development and is often associated with ciliopathies." (PMID 37085629, 2023).
autoimmune conditions (1 paper, 2017). "Novel gene-longevity associations included genes MICA/B (a locus previously linked to autoimmune conditions rheumatoid arthritis and multiple sclerosis), TOX, ZW10, SEMA6D, EGLN2/CYP2A6, EXOC3L2/MARK4 and C20orf187." (PMID 29227965, 2017).
bone marrow failure (1 paper, 2022). "There are two other reports indicating that biallelic mutations of EXOC3L2 causes developmental anomalies, such as peritrigonal and cerebellar abnormalities, with enlargement of ventricular trigones, pituitary hypoplasia, severe renal dysplasia and bone marrow failure." (PMID 36362885, 2022).
tumor (2 papers, 2021 to 2022). "First, gene-level differential analysis of the stromal component of KIRC against the other eight tumor types revealed 941 differentially expressed (DE) genes (q< 0.05, BH adjusted), including the Mcf2l, Exoc3l2, Olfr558, and Chrm2 listed as the top-ranked genes." (PMID 35079698, 2021). "However, role of Exoc3l2 on pathological angiogenesis such as tumour angiogenesis remains unclear." (PMID 36362885, 2022).
EXOC3L2 also shares sentences with these, for which no sentence is quoted: cancer (3 papers); dementia (2); Parkinson’s (2); ataxia-telangiectasia and (1); brain disorder (1); cardiovascular diseases (1); cognitive decline (1); colorectal cancer (1); dyslipidemia (1); mammary tumor (1); Meckel-Gruber syndrome (1); multiple sclerosis (1); myeloma (1); renal dysplasia (1); rheumatoid arthritis (1); Stroke (1); type 2 diabetes (1).